CGA (glycoprotein hormones, alpha polypeptide)
Diseases named in the same sentence as CGA in open-access papers (continued):
Sharing a sentence is not in itself a finding about the gene and the disease.
prostate carcinoma (continued). "Combined with the results of our pooled analyses, we suggest that elevated circulating CgA is suggestive of poorer OS and PFS in prostate cancer, and the results of our meta-analysis and sensitivity analysis reflect rationality and reliability." (PMID 39975592, 2025). "Overexpression of NK1R in epithelial prostate cancer cells was able to induce a shift of lineage plasticity, leading to the reduction of AR and PSA levels, the gain of the expression of CgA, ENO2, AURKA, N-Myc, MYT1, and SRRM4." (PMID 37385990, 2023). "Of further interest, when the prostate cancer cell lines LNCaP and PC346-C were transduced with the neuroendocrine-selective Ad[CgA-LUC] vector and then treated with FK228 or VPA, we found that transgene expression was increased." (PMID 21379379, 2011). "Our study demonstrated focal NED in biopsies in 14 of 18 metastatic conventional prostate cancer cases, in contrast to 21 non-metastatic cases all without any cgA positivity." (PMID 20535283, 2010). "However, other studies suggest that circulating CgA levels are not significantly different between the two and that detection of circulating CgA does not provide useful value in diagnosing prostate cancer." (PMID 39975592, 2025). "Notably, elevated levels of CgA have also been observed in several non-neuroendocrine carcinomas (NECs), such as lung, breast, and prostate carcinomas." (PMID 38835066, 2024). "We also compared measured CgA levels in samples from patients with three different disease entities (NETs, non-NET pancreatic tumors, and prostate cancer) to healthy individuals to determine whether serum CgA can be used to discriminate among these groups." (PMID 34943638, 2021). "Co-incidentally, the expression of neuromimicry genes including CgA and NSE, elevated in prostate cancer KRT13-overexpresing cells, was not elevated in breast cancer MCF7-KRT13 cells." (PMID 35078507, 2022). "CgA measured using KRYPTOR on samples from patients within the three study cohorts (NETs, non-NET pancreatic tumors, prostate cancer) and from healthy individuals were compared with the Mann–Whitney U test." (PMID 34943638, 2021). "These factors may have contributed to the absence of significant differences in CgA levels for samples from patients with NETs, non-NET pancreatic tumors, and prostate cancer." (PMID 34943638, 2021). "We found that CgA levels from patients with NETs were significantly higher than from healthy individuals, whereas those from patients with non-NET pancreatic tumors and prostate cancer were not significantly different from healthy individuals." (PMID 34943638, 2021). "Median CgA levels in patients with NETs (n = 57), non-NET pancreatic tumors (n = 12), and prostate cancer (n = 16) were 1.74 log ng/mL (interquartile range (IQR): 0.87 log ng/mL), 1.75 log ng/mL (IQR: 0.44 log ng/mL), and 1.80 log ng/mL (IQR: 0.29 log ng/mL), respectively." (PMID 34943638, 2021).
pancreatic NETs (19 papers, 2003 to 2025). "Studies reporting an association between CgA levels and tumor location observed the highest values in ileal NETs; pancreatic NETs exhibit intermediate values; and gastric, pituitary, and parathyroid tumors had even lower values than healthy individuals." (PMID 34943638, 2021). "Although serum CgA has been widely used as a diagnostic biomarker in pancreatic neuroendocrine tumors, it has a limited role, especially with localized diseases." (PMID 32903471, 2020). "We investigated the diagnostic value of circulating miRNAs along with CgA in pancreatic neuroendocrine tumors (pNET)." (PMID 32887459, 2020). "In patients with multiple endocrine neoplasia type 1 (MEN1) followed up at ENETS centers of Excellence, chromogranin A (CgA) and pancreatic polypeptide (PP) are widely used screening tools for pancreatic neuroendocrine tumors (panNETs)." (PMID 40455177, 2025). "Of note, a recent survey in 56 ENETS centers of excellence demonstrated that a majority, i.e. 69% of the centers still use CgA and 38% PP in the screening of duodeno-pancreatic NETs in patients with MEN1." (PMID 40455177, 2025). "In the context of pancreatic neuroendocrine tumors, CGA expression is commonly detected, with a trend indicating that tumors with metastases exhibit reduced CGA protein levels compared to those confined to the primary site." (PMID 39588299, 2024). "In pancreatic NETs, several studies showed that CgA is a good tool to predict tumor relapse after surgery; whereas, other studies concluded that CgA has a limited value." (PMID 37685358, 2023). "In the diagnosis of pancreatic NETs, the determination of CgA and pancreatic polypeptide is significantly useful." (PMID 36289922, 2022). "have reported that 79% of 445 small pancreatic NET (≤2 cm) patients were categorized with low CgA at a cut off value of 420 ng/ml." (PMID 34868938, 2021). "The associated literatures on this issue were reviewed and certain studies found that specific SPTP patients were misdiagnosed with pancreatic neuroendocrine tumors even though expression of Syn and CgA was positive." (PMID 24932294, 2014). "High CgA levels correlate with tumor burden and are considered as a predictor of bad prognosis in both midgut and pancreatic NETs." (PMID 24213232, 2012). "The sensitivity of AP and the correlations of AP/CgA-data-pairs were low in both midgut and pancreatic NETs, although highest for metastatic pancreatic NETs." (PMID 24213232, 2012). "A recent study found that CgA is associated with disease progression in pancreatic NETs and predictive of negative outcome in patients with small intestine or cecum NETs, however, the results were limited to these subgroups." (PMID 37770647, 2024). "This may be particularly useful in pancreatic NETs (<20% had elevated CgA levels in the current study)." (PMID 25316294, 2014). "We further investigated the sensitivity of AP in midgut and pancreatic NET patients depending on the presence of liver metastases, and examined if there was a significant correlation between serum CgA levels and serum AP levels in pancreatic and midgut NET patients." (PMID 24213232, 2012). "Thirty-five pancreatic neuroendocrine tumors (Pan-NETs) were studied, consisting of 14 insulinomas, 8 gastrinomas, 2 glucagonomas, 6 pancreatic polypeptidomas and 5 non-functioning tumors, and were immunostained for four pancreatic hormones, gastrin, CgA, and SPY." (PMID 32020844, 2020). "The patients with low baseline CgA levels had significantly better OS in pancreatic NETs (survival rate 96.6% vs 57.1%, P=0.0002) but not in non-pancreatic NETs (survival rate 100% vs 87.9%, P=0.317)." (PMID 34868938, 2021). "Similarly, negativity for neuroendocrine markers (Syn, CgA, and CD56) excludes a pancreatic neuroendocrine tumor.​​ CD34 negativity​​ helps exclude a ​​solitary fibrous tumor." (PMID 41244919, 2025).
diabetes (17 papers, 2016 to 2026). "Chromogranin A (CgA), B (CgB), and C (CgC), the family members of the granin glycoproteins, are associated with diabetes." (PMID 34204153, 2021). "As clinical biomarkers, CgA, CgB, CgC, and derived polypeptides are closely associated with atherosclerotic cardiovascular diseases and diabetes." (PMID 34204153, 2021). "Knockout mouse models further demonstrate that loss of CgA or CST profoundly alters glucose homeostasis, macrophage polarization, catecholamine release, and diabetes susceptibility." (PMID 42051247, 2026). "CgA, WE-14, and other less-known CgA-derived peptides have also been reported to trigger autoimmune responses, highly studied in type 1 diabetes mellitus." (PMID 40370467, 2025). "A previous study documented the clinical value of measurements of CgA as a potential marker for diabetes." (PMID 35062888, 2022). "The Spearman rank correlation test demonstrated that there was a moderate-intensity positive correlation between serum CgA levels and known diabetes durations and UACRs in all subjects (P < 0.001)." (PMID 35062888, 2022). "So the most important finding of our study is that CgA correlated not only with eGFR and the presence of diabetes, which have already been shown in previous studies, but also with UACR and this correlation appeared even stronger than others." (PMID 35062888, 2022). "There was a moderate-intensity positive correlation between serum CgA levels and known diabetes durations and UACRs in all subjects." (PMID 35062888, 2022). "This review introduces the emerging roles of CgA, CgB, CgC, and derived polypeptides in the multicellular pathogenesis and development of atherosclerosis, diabetes, and coronary heart disease." (PMID 34204153, 2021). "Due to their effects on immune homeostasis, CST and other CgA-derived peptides are promising targets for diagnosis and therapy of diseases with an inflammatory component, such as diabetes, cancer and RA." (PMID 30337922, 2018). "CgA was also proposed as an important biomarker in diabetes." (PMID 31750312, 2019). "This makes CgA particularly interesting in the context of metabolic diseases, such as diabetes." (PMID 30337922, 2018). "Collectively, these findings identify CgA-derived peptides as critical regulators of islet function and highlight CST as a promising therapeutic candidate for diabetes and metabolic-inflammatory disorders." (PMID 41298823, 2025). "Interestingly, CgA and CgB levels did not correlate with each other and changed in different directions in type 1 diabetes mellitus." (PMID 32684986, 2020). "Using donor tissue immunolabeled for CgA and CK19 (n = 45; HDBR n = 10, EADB n = 35), we quantified total EO density and percentage of endocrine area in donors without diabetes." (PMID 41223263, 2025). "Lack of CgA-derived autoantigens in CHGA gene knockout NOD mice, however, may not be the only mechanism protecting from diabetes." (PMID 40370467, 2025).
heart failure (17 papers, 2014 to 2025). Inability of the heart to pump blood at an adequate rate to meet tissue metabolic requirements. "Elevated CgA plasma levels are associated with mortality risk in patients with myocardial infarction, acute coronary syndrome and heart failure." (PMID 35468164, 2022). "High concentrations of CgA were independently associated with 1-year death and hospitalization for heart failure." (PMID 35743683, 2022). "CgA measurement in the plasma of elderly patients with symptoms of heart failure can identify those at increased risk of short- and long-term mortality." (PMID 24532383, 2014). "The present study shows that CgA measurement in elderly patients presenting with symptoms of heart failure can identify those at increased risk of both short- and long-term mortality." (PMID 24532383, 2014). "We examined whether chromogranin A (CgA) measurement in plasma may be valuable in assessing risk of death in elderly patients with symptoms of heart failure in a primary care setting." (PMID 24532383, 2014). "By using an assay that measures all forms of CgA in plasma, accurate quantitation could be achieved that contains information beyond a ‘gold standard’ risk marker in heart failure: thus, the data suggest for the first time that CgA plasma measurement may be a general risk marker in elderly patients." (PMID 24532383, 2014). "In the current state of research, CgA plasma measurement as a biomarker in heart failure is still being explored and cannot be recommended for general use." (PMID 35743683, 2022). "Decreased NE in old WT and young CgA-KO mice indicates increased cardiac and renal spillover of NE, which is common in hypertensive and heart failure patients." (PMID 36440192, 2022). "For now, we conclude that CgA plasma measurement by using the new CgA measurement assay in heart failure patients is useful as earlier suggested, and that the marker can even be applied in patients with symptoms suggestive of the condition." (PMID 24532383, 2014). "In the cardiological setting, CgA measurement has only been explored in small patient cohorts with acute coronary syndrome or heart failure." (PMID 24532383, 2014). "For now, CgA plasma measurement as a biomarker in heart failure is still only examined in highly selected patients and cannot be recommended for general use." (PMID 24532383, 2014). "In CAD patients, plasma CgA levels rise even higher in the presence of heart failure." (PMID 34204153, 2021). "Even though the CI is wide, we suggest that CgA measurement in heart failure patients may have the largest clinical potential in ‘the grey zone’ patients with natriuretic peptide levels below the presently set diagnostic cutoff values." (PMID 24532383, 2014). "Neuroendocrine tumour cells secrete CgA and serotonin, the precursor of 5-HIAA, which thus reflect the disease burden while proBNP is a marker of cardiac failure, mainly secreted by atrial and ventricular myocytes in response to cardiac wall stress." (PMID 35536452, 2022). "There are higher plasma levels of CgA, CgB, catestatin, VIF, and secretoneurin in patients with heart failure compared with healthy control groups of patients." (PMID 34204153, 2021). "After adding the gold standard biomarker for heart failure (NT-proBNP) into the model (model III), the CgA confirm test still exhibited significant and independent prognostic information (HR 3.61, 95% CI 1.42–9.15)." (PMID 24532383, 2014).
small cell carcinoma (15 papers, 2012 to 2025). A neuroendocrine carcinoma composed of small malignant cells which are often said to resemble "oat cells" under the microscope. "Both specimens suggested small cell carcinoma, and immunohistochemistry analysis showed positive expression of neuroendocrine-related markers such as Syn, CgA, CD56 in both specimens." (PMID 40071100, 2025). "Neuroendocrine malignancies, such as small cell carcinoma, are characterised by distinctive biomarkers, including chromogranin A (CgA) and synaptophysin." (PMID 38149143, 2023). "It is true that CgA and Syn expression is very limited among small round-cell tumors, being confined to esthesioneuroblastomas, differentiating neuroblastomas, and small cell carcinomas, including Merkel cell carcinoma." (PMID 35372059, 2022). "Mild elevation of CgA has also been detected in some benign or malignant cancers, such as parathyroid adenoma, thyroid cancer, hepatocellular carcinoma, and lung cancer (small cell carcinoma and non-small cell carcinoma)." (PMID 34868938, 2021). "In the case of small cell carcinoma, immunoreactivity for CgA and synaptophysin was evident only focally." (PMID 24695372, 2014). "In addition, immunoreactivity with TTF-1 and neuroendocrine markers (Syn, CgA, etc.)will support the diagnosis of small cell carcinoma." (PMID 36290813, 2022). "CTC detection by morphology-based enrichment methods could potentially become an alternative to tissue re-biopsy for detection of histologic transformation since these CTCs could undergo cytopathological analysis (i.e., positivity for CD56, CgA, or Syn in case of small cell carcinoma)." (PMID 34066817, 2021). "However, CgA is less useful for detecting PanNEC tumors, especially in small cell carcinoma." (PMID 33101770, 2020). "Furthermore, immunohistochemical staining for specific neuroendocrine markers, including CD56, neuron-specific enolase, Syn and CgA, may distinguish neuroendocrine small cell carcinoma from other tumors and be useful for determining the correct diagnosis." (PMID 24520292, 2014). "INSM1 showed similar sensitivity (93.9%) to SYN (93.9%), CgA (87.8%), and CD56 (87.8%) in all 33 small cell carcinomas or carcinomas with small cell carcinoma components." (PMID 34943408, 2021). "Rhabdomyosarcoma expresses desmin, MyoD1, or myogenin due to skeletal muscle differentiation, whereas small cell carcinoma expresses CK and CgA with or without Syn." (PMID 40978053, 2025). "In the case of small cell carcinoma, immunohistological detection of CgA was negative, synaptophysin was focally positive and proliferative activity of tumour cells (Ki-67 index) was higher than 80%." (PMID 24695372, 2014). "Our Pan-NETs were well-differentiated, and CgA immunostaining should be compared among the Pan-NETs of the same differentiation since less differentiated PET may not show strong CgA staining than well-differentiated ones such as CgA-negative small cell carcinoma." (PMID 32020844, 2020). "In a study on 49 gynecologic NECs (4 vagina, 39 cervix, 5 cases of endometrium, and 1 ovary), INSM1 expression was more diffuse and intense compared to SYN, CgA, and CD56 for cervical small cell NECs but not for large cell NECs." (PMID 34943408, 2021).
atrophic gastritis (14 papers, 2012 to 2025). "PPI treatment, impaired renal function and atrophic gastritis can also yield false positive CgA concentrations." (PMID 40455177, 2025). "Reasons for false positive CgA elevation include renal disease, Parkinson disease, uncontrolled hypertension, pregnancy, hypergastrinemia, chronic atrophic gastritis, among others." (PMID 36950054, 2023). "It is important to remember that false-positive elevation of CgA is presented in many clinical settings like impaired renal function, chronic inflammations, chronic atrophic gastritis (type A), use of Proton Pump Inhibitors, glucocorticosteroids or others." (PMID 34917031, 2021). "It has been reported that the elevated levels of CgA correlate significantly with carcinoid heart disease, treatment of proton pump inhibitors, chronic atrophic gastritis, and impaired renal function." (PMID 30416612, 2018). "Atrophic gastritis, which often results in increased gastrin levels, is characterized by elevated CgA plasma levels." (PMID 29232390, 2017). "However, CgA has limitations because elevated CgA levels can occur in chronic atrophic gastritis, inflammatory diseases, renal/liver impairment, and during proton pump inhibitor treatment." (PMID 37444393, 2023). "The most frequent causes of falsely (non-NET) elevated CgA levels in clinical practice are the use of PPIs, the presence of chronic atrophic gastritis, and impairment of kidney function." (PMID 34943638, 2021). "A third explanation is that pre-existing conditions such as chronic atrophic gastritis, use of protein proton inhibitors as well as impaired kidney function may affect CgA levels." (PMID 27159453, 2016). "However, CgA is also known to be false positive in some cases, for example in patients with multiple myeloma, renal impairment, atrophic gastritis or proton pump inhibitor therapy." (PMID 22269186, 2012). "However, a wide range of non-NET conditions are associated with elevated plasma CgA concentrations such as chronic atrophic gastritis, renal and hepatic dysfunction, cardiovascular disease, and rheumatologic disease." (PMID 33138020, 2020). "Furthermore, CgA seems to not be a reliable indicator of recurrences, and a false increase in this biomarker can be common in the context of atrophic gastritis or after proton pump inhibitor treatment and renal and liver diseases." (PMID 39590202, 2024).
inflammatory bowel disease (14 papers, 2016 to 2025). A spectrum of small and large bowel inflammatory diseases of unknown etiology. "Marked elevation of CgA can occur with the use of proton pump inhibitors (PPIs) or in conditions like atrophic gastritis, inflammatory bowel disease (IBD), irritable bowel syndrome (IBS), renal failure, hyperthyroidism, heart failure, hypertension, or prostate cancer." (PMID 33884247, 2021). "CgA is a member of the granine peptides, which are secreted in nervous, endocrine, and immune cells under stress and during active periods of gut –related diseases such as Irritable Bowel Syndrome and Inflammatory Bowel Disease." (PMID 27694811, 2016). "In inflammatory bowel diseases (IBD), the mucosal inflammation is characterized by an alteration of CgA production." (PMID 36090980, 2022).